NDFIP1 (Nedd4 family interacting protein 1)
Diseases named in the same sentence as NDFIP1 in open-access papers (continued):
Sharing a sentence is not in itself a finding about the gene and the disease.
tumor (10 papers, 2014 to 2025). "And vice versa, the overexpression of NDFIP1 resulted in smaller tumor size and weight, lower level of PCNA and Ki-67 in vivo." (PMID 36929005, 2023). "So, our data not only extend the tumor-suppressing function of NDFIP1 to NSCLC, but also provide a new downstream mechanism related to cellular and exosomal TAZ." (PMID 36929005, 2023). "In summary, our data uncover a new tumor suppressor, NDFIP1 in NSCLC, and a new exosome-related regulatory mechanism of TAZ." (PMID 36929005, 2023). "This study has identified a new tumor suppressor, NDFIP1 in NSCLC, and its novel function in controlling the quantity of cellular and exosomal TAZ." (PMID 36929005, 2023). "Then the stably transfected SPC-A1 cells were subcutaneously injected into the right flanks of BALB/c nude mice (n = 6), and a marked increase in tumor size and weight was observed in mice receiving the NDFIP1 knockout cells." (PMID 36929005, 2023). "Previously, NDFIP1 has been reported as a tumor suppressor in other tumor types and can be downregulated by upstream miRNAs or external stimuli such as hypoxia and nicotine." (PMID 36929005, 2023). "Taken together, our data have disclosed NDFIP1 as a novel tumor suppressor and proposed a new exosome-related regulatory mechanism of TAZ, providing new insights for the development of biomarkers and treatment strategies of NSCLC." (PMID 36929005, 2023). "Experimental studies have revealed that NDFIP1 has potential anti-tumor effects in multiple malignant diseases." (PMID 35264565, 2022). "NDFIP1 also acts as a tumour suppressor by repressing cell proliferation and was reported to be down-regulated in human uveal melamoma." (PMID 30836959, 2019). "Overall, these findings suggested NDFIP1 as a tumor suppressor in NSCLC." (PMID 36929005, 2023). "Also, the TAZ level in equal number of exosomes was lower in tumor cells with lower NDFIP1 expression." (PMID 36929005, 2023). "In addition, exosomal TAZ was positively correlated with NDFIP1 in tumor tissues, and the TAZ in tumor cells had a negative correlation with the exosomal TAZ, indicating that NDFIP1 acted as the molecular switch of intra- and extra-cellular TAZ." (PMID 36929005, 2023). "In the light of the findings in this study, low NDFIP1 level in tumor tissues and low TAZ level in single serum exosome may serve as diagnostic indexes for NSCLC, although a larger sample size is needed in the future study." (PMID 36929005, 2023). "Since TAZ mainly drives tumor growth, we further tested whether NDFIP1 had an effect on NSCLC proliferation." (PMID 36929005, 2023). "And cellular TAZ was negatively correlated with NDFIP1 in tumor tissues." (PMID 36929005, 2023). "NDFIP1 protein levels were lower in tumor samples than that in matched paratumor samples." (PMID 36929005, 2023). "Furthermore, we have shown for the first time that NDFIP1 inhibits tumor cell proliferation in NSCLC through the regulation of TAZ." (PMID 36929005, 2023). "NDFIP1 has been previously reported as a tumor suppressor in multiple solid tumors, but the function of NDFIP1 in NSCLC and the underlying mechanism are still unknown." (PMID 36929005, 2023). "Accordingly, our study provides more evidence that NDFIP1 functions in tumor inhibition." (PMID 35264565, 2022). "Recently, several studies have reported that NDFIP1 acts as a critical tumor suppressor." (PMID 35264565, 2022). "It should also be noted that Ndfip1 has a number of other protein targets, including PTEN a major tumor suppressor protein which has roles in cell survival pathways, as such the role of Ndfip1 in PD could be multifaceted and involve divergent pathways within the cell." (PMID 24475238, 2014). "Then combining evidences from clinical data, in vitro and in vivo experiments, we revealed that lower NDFIP1 led to lower TAZ packaged in exosomes and higher TAZ accumulation in cells, promoting cell proliferation and tumor growth eventually." (PMID 36929005, 2023).
tumor (continued). "Nedd4 family interacting protein 1 (Ndfip1) is inhibited in GBM, which prevents PTEN from accumulating in the nucleus and hence enhances tumour cell survival and proliferation." (PMID 35716231, 2022). "Additionally, analysis of iron metabolism-related gene expression revealed a downregulation of NDFIP1 and BOLA3 in tumor tissues." (PMID 39654899, 2024). "In conclusion, NDFIP1 plays an essential role in the recruitment of TAZ into exosomes, therefore balancing the levels of intracellular and extracellular TAZ; NDFIP1, as a tumor suppressor, is downregulated in NSCLC, therefore releasing the brake of cell proliferation inhibition." (PMID 36929005, 2023). "Western blotting showed that the levels of WWP1 were elevated in tumor tissues with low expression levels of NDFIP1, indicating a negative correlation between WWP1 expression and NDFIP1 in clinical cases." (PMID 35264565, 2022). "MiR-155 showed increased levels in tumor tissues compared to paired normal tissues in a cohort of twenty-five UM patients; upregulation of miR-155 enhanced cell proliferation and invasion of UM cell lines through the target NDFIP1 (Nedd4 family interacting protein 1)." (PMID 36765733, 2023). "However, whether WW domain-containing transcription regulator 1 (WWTR1, also known as TAZ) can be packaged into exosomes by NDFIP1 and if so, whether the release of this oncogenic protein via exosomes has an effect on tumor development has not been investigated to any extent." (PMID 36929005, 2023).
cancer (3 papers, 2021 to 2023). A tumor composed of atypical neoplastic, often pleomorphic cells that invade other tissues. "Indeed, downregulation of ENTREP is seen in various types of cancer, whereas NDFIP1, NDFIP2, and N4BP1 are infrequently downregulated (Fig EV4A)." (PMID 34927784, 2022).
infection (3 papers, 2020 to 2025). The state of being infected such as from the introduction of a foreign agent such as serum, vaccine, antigenic substance or organism. "Among those GO terms, at the acute infection stage, some targeted DEmRNAs (e.g., Ccl2, Lgals3, H2-DMb2, Ripk2, and Ndfip1) were enriched in the “regulation of T cell activation” term (GO:0050863)." (PMID 38229193, 2024). "Ad.Ndfip1 infection induced an obvious increase in the protein levels of Ndfip1 after exposure to rotenone." (PMID 33469419, 2020). "The expression of Ndfip1 was detected after Ad.Ndfip1 or Ad.GFP infection in SH-SY5Y cells for 48 h." (PMID 33469419, 2020). "Then after infection of A53T-α-syn iPC12 cells or WT-α-syn iPC12 cells with Ad.Ndfip1 or Ad.GFP for 24 h, doxycline was added to iPC12 cells for another 24 h to induced the expression of α-syn." (PMID 33469419, 2020). "Data showed that the expression of Ndfip1 increased significantly in the SH-SY5Y cells with infection of Ad.Ndfip1 compared with Ad.GFP infected cells and the normal controls." (PMID 33469419, 2020).
immune disease (1 paper, 2022). "Among those, six gene knockouts resulted in an immune disease, including Cd28, Ndfip1, Skap2, Tmem258, Tnfrsf1a, and Tnfrsf9." (PMID 35591976, 2022).
NDFIP1 also shares sentences with these, for which no sentence is quoted: neurotoxicity (2 papers); adult onset asthma (1); Airway obstruction (1); allergic asthma (1); Alzheimer disease (1); cerebral palsy (1); degenerative disease (1); eczema (1); glioblastoma (1); hay fever (1); inflammation (1); kidney cancer (1); liver fibrosis (1); multiple sclerosis (1); neurological disorders (1); Onset (1); Parkinson's (1); Rett syndrome (1); spinal cord injury (1); thyroiditis (1); uveal melanoma (1).